NCS1 (neuronal calcium sensor 1)
Diseases named in the same sentence as NCS1 in open-access papers (continued):
Sharing a sentence is not in itself a finding about the gene and the disease.
tumor (continued). "This reveals that NCS1 may function as a modulator of tumor immune escape and contribute to ICB resistance." (PMID 37893139, 2023). "It was observed that both miR-144-5p and miR-144-3p had tumor inhibitory effects by targeting several oncogenes in squamous NSCLC including neuronal calcium sensor 1 (NCS1), solute carrier family 44 member 5 (SLC44A5), and myristoylated alanine rich protein kinase C substrate (MARCKS) genes." (PMID 32276343, 2020). "Our results raise the possibility that targeting the NFκB‐activating tumor microenvironment could prevent up‐regulation of NCS1 and other stress response proteins that consequently lead to a more aggressive tumor phenotype." (PMID 32239615, 2020). "Studies have demonstrated correlations between the levels of NCS1 expression and the numbers of TILs, immunosuppressants, immunostimulants, MHC molecules, chemokines, and chemokine receptors in different tumor types." (PMID 37893139, 2023). "According to the ICSDB database, NCS1 knockdown after CRISPR inhibited the proliferation of PRAD, PAAD, and GBM cell lines, providing a reference for subsequent cytological experiments to test the effect of NCS1 knockdown on tumor cell proliferation." (PMID 37893139, 2023). "After confirming the role of NCS1 in immunotherapy, univariate and multivariate COX regression analyses were conducted to construct KM curves, further determining the effect of NCS1 on the survival of tumor patients." (PMID 37893139, 2023).
peripheral neuropathy (7 papers, 2016 to 2024). A disorder affecting the peripheral nervous system. "Because we previously reported the importance of NCS1 for a type of peripheral neuropathy induced by paclitaxel administration, we aimed to find out if constitutive NCS1 deficiency would affect components of the peripheral nervous system." (PMID 33504822, 2021). "These NCS-1 dependent changes in intracellular signaling have been associated with chemotherapy induced peripheral neuropathy." (PMID 27575489, 2016). "We previously elucidated a mechanism for paclitaxel-induced peripheral neuropathy, in which paclitaxel binds neuronal calcium sensor 1 (NCS1) to induce spontaneous InsP3R-dependent calcium oscillations." (PMID 34174909, 2021). "We previously reported that NCS1 expression was reduced following paclitaxel-induced peripheral neuropathy." (PMID 33504822, 2021). "Overall, we found that a constitutive loss of NCS1 did not markedly alter sensory or motor performance in mice, and NCS1-KO mice did not exhibit peripheral neuropathy." (PMID 33504822, 2021). "In addition, calpain has been shown to degrade neuronal calcium sensor 1 (NCS-1) following paclitaxel treatment which is important in irreversible peripheral neuropathy." (PMID 27323818, 2016).
neurodegenerative disease (6 papers, 2018 to 2023). A disorder of the central nervous system characterized by gradual and progressive loss of neural tissue and neurologic function. "Altered NCS1 expression is associated with neurodevelopmental and neurodegenerative diseases." (PMID 33504822, 2021). "NCS-1 is involved in the genesis of a number of neurodegenerative diseases—in sleep-wake disturbance symptoms in bipolar disease, autism, Parkinson’s disease, and is also involved in the induction of cocaine addiction." (PMID 36555318, 2022). "Thus, the lack of knowledge of the molecular mechanisms of the regulation of the processes of neurotransmission by the NCS-1 protein, the survival of neurons, and the genesis of neurodegenerative diseases, necessitates their study." (PMID 36555318, 2022). "There are no direct indications concerning the involvement of NCS-1 in the pathogenesis of neurodegenerative diseases." (PMID 30618610, 2018).
neurological diseases (4 papers, 2016 to 2023). "Because alterations in the level of expression of NCS-1 Var1 and the expression of NCS-1 variants have been correlated with several neurological diseases, the relative expression and functional role of NCS-1 Var2 was examined." (PMID 27575489, 2016). "Given the interest in the NCS-1/Ric-8A complex as a therapeutic target in nervous system disorders, it is necessary to shed light on this molecular mechanism of action at atomic level." (PMID 38018500, 2023). "We found that low-doses of Li or VPA, agents commonly used to treat psychiatric and neurologic disorders with a well understood safety profile, inhibit the actions of NCS1 and prevent CIPN in animal models." (PMID 29484113, 2018). "As other groups and we have proposed NCS1 as a pharmacological target for treating various neurological diseases, particularly neurodevelopmental and psychiatric diseases, future studies will also benefit from considering potential sex-specific differences in NCS1 functions." (PMID 33504822, 2021).
psychiatric disorder (3 papers, 2019 to 2022). A disorder characterized by behavioral and/or psychological abnormalities, often accompanied by physical symptoms. "In future studies, the generation of mouse lines with specific tissue-specific NCS-1-deficiencies may provide further insights into a potential genetic link between some psychiatric disorders and the risk of being obese." (PMID 31001084, 2019). "Given the association of altered NCS-1 expression with behaviorial abnormalities, NCS-1−/− mice may offer an interesting perspective for studying in a mouse model a potential genetic link between some psychiatric disorders and the risk of being obese." (PMID 31001084, 2019).
neurodevelopmental disorder (2 papers, 2022 to 2023). A behavioral and cognitive disorder with onset during the developmental period that involves impaired or aberrant development of intellectual, motor, or social functions. "In summary, we have taken a step toward establishing the inhibition of the NCS-1/Ric8a complex as a treatment for FXS or other neurodevelopmental disorders associated with synaptic homeostasis dysfunction." (PMID 36466176, 2022). "In neurodevelopmental disorders, where synapse number is abnormally high, the inhibition of the NCS-1/Ric-8A complex formation reduces synapse number and improves learning in Fragile X syndrome animal models." (PMID 38018500, 2023). "Neuronal calcium sensor 1 (NCS-1), through its interaction with the guanine-exchange factor Ric8a, regulates the number of synapses and the probability of the release of a neurotransmitter, the two neuronal features that are altered in FXS and other neurodevelopmental disorders." (PMID 36466176, 2022).
hematologic malignancies (1 paper, 2023). "NCS1 has been suggested to enhance the function and persistence of chimeric antigen receptor T-cell immunotherapy (CAR-T) cells via TH17 cells in hematologic malignancies." (PMID 37893139, 2023).
infection (1 paper, 2020). The state of being infected such as from the introduction of a foreign agent such as serum, vaccine, antigenic substance or organism. "Ncs1 deficiency coincided with reduced growth, characterized by delayed bud emergence and aberrant cell division, and hypovirulence in a mouse infection model." (PMID 32907953, 2020).
NCS1 also shares sentences with these, for which no sentence is quoted: amyotrophic lateral sclerosis (1 paper); bile duct cancer (1); Bladder Cancer (1); breast tumor (1); Cerebral ischemia (1); Colon Cancer (1); COVID-19 (1); endometrial cancer (1); epilepsy (1); esophageal cancer (1); head and neck cancer (1); Hyperglycemia (1); Hyperinsulinemia (1); Kidney Clear Cell Carcinoma (1); lung adenocarcinoma (1); Lung Squamous Cell Carcinoma (1); melanoma (1); mesothelioma (1); mood disturbances (1); movement disorder (1); multiple sclerosis (1); ocular melanoma (1); paraganglioma (1); periodontitis (1); pheochromocytoma (1); polyneuropathy (1); sarcoma (1); Skin Cutaneous Melanoma (1); testicular cancer (1); thyroid cancer (1).